PCDH18 (protocadherin 18)
Description:
Potential calcium-dependent cell-adhesion protein.
Synonyms: KIAA1562; PCDH68L
Tractability: Antibody: UniProt places it where antibodies can reach, with medium confidence; UniProt predicts a signal peptide or a membrane-spanning region; its Gene Ontology location is reachable by antibodies, with medium confidence.
Gene: Protein-coding gene on chromosome 4 (137,518,918 to 137,532,494, reverse strand). Ensembl gene ENSG00000189184.
Subcellular location: Cell membrane
Subcellular location (Human Protein Atlas): Cytosol; Golgi apparatus
Gene Ontology:
Molecular function: protein binding; cell adhesion molecule binding; calcium ion binding
Biological process: brain development; cell adhesion; homophilic cell-cell adhesion
Cellular component: plasma membrane; membrane
Genetic constraint (gnomAD): Loss-of-function variants: 36 observed, 70.65 expected, observed/expected ratio (o/e) 0.51, 90% interval 0.39 to 0.67. The upper end of that interval is the gene's LOEUF score, 0.67, which puts it in group 2 of 6, group 1 being the genes least tolerant of losing a copy. Missense variants: 1,330 observed, 1,450.3 expected, observed/expected ratio (o/e) 0.92, 90% interval 0.88 to 0.96. Synonymous variants: 565 observed, 532.59 expected, observed/expected ratio (o/e) 1.06, 90% interval 0.99 to 1.14.
Homologues: Orthologues: chimpanzee PCDH18 (99% identical), macaque PCDH18 (99% identical), pig PCDH18 (97% identical), guinea pig PCDH18 (96% identical), rabbit PCDH18 (95% identical), mouse Pcdh18 (93% identical), rat Pcdh18 (92% identical), dog PCDH18 (91% identical), tropical clawed frog pcdh18 (80% identical), zebrafish pcdh18b (68% identical), zebrafish pcdh18a (67% identical). Paralogues in human: PCDH8 (33% identical), PCDH17 (31% identical), PCDH19 (30% identical), PCDH10 (27% identical), PCDH12 (27% identical), PCDHA1 (25% identical), PCDHA2 (25% identical), PCDHA3 (25% identical), PCDHA4 (25% identical), PCDHGA4 (25% identical), PCDHA13 (25% identical), PCDHB15 (25% identical), and 49 more.
Diseases named in the same sentence as PCDH18 in open-access papers:
PCDH18 is named in the same sentence as 19 diseases in open-access papers, as found by Europe PMC text mining. Sharing a sentence is not in itself a finding about the gene and the disease. The quoted sentences say what the papers report.
melanoma (3 papers, 2018 to 2023). A malignant, usually aggressive tumor composed of atypical, neoplastic melanocytes. "Last, strongly downregulated genes included Pcdh18, a tumor suppressor in CRC, and Nectin which might drive melanoma cell proliferation upon loss of these genes." (PMID 37179302, 2023).
Intellectual disability (2 papers, 2017 to 2021). "Although the function of PCDH18 in humans is unclear, some studies have shown that PCDH18 deletion may be associated with altered brain development, intellectual disability, and multiple malformations with pulmonary hypertension." (PMID 29075151, 2017).
bladder carcinoma (1 paper, 2017). "Among the remaining genes, LAMA2 (selected in 16 out of 20 folds) has been detected as a driver gene in head and neck squamous cell carcinoma and PCDH18 (selected in 11 out of 20 folds) has been detected as a driver in bladder carcinoma, cutaneous melanoma and in a pan-cancer analysis setting." (PMID 28650955, 2017).
colorectal cancer (1 paper, 2017). A primary or metastatic malignant neoplasm that affects the colon or rectum. "In contrast, the methylation and expression level of PCDH18 did not change significantly after 5-AZA treatment in NCM460 cells, strongly indicating that CpG island hypermethylation was responsible for loss or decreased expression of PCDH18 in colorectal cancer." (PMID 28588296, 2017). "In our study, we identified and characterized a potential biomarker, PCDH18, in colorectal cancer that involved in cell proliferation and migration through the Wnt/β-catenin signaling pathway." (PMID 28588296, 2017). "In our present study, we have identified PCDH18 as a candidate biomarker for diagnosis of colorectal cancer and a candidate TSG for CRC." (PMID 28588296, 2017). "Protocadherin18 (PCDH18) was found to be preferentially methylated and inactivated in colorectal cancer (CRC) using bioinformatics tools." (PMID 28588296, 2017). "Our results will be useful for clarification of the relationship between PCDH18 methylation and its expression, thereby providing a candidate therapeutic target for the treatment of colorectal cancer." (PMID 28588296, 2017). "In this study, we identified that PCDH18 was preferentially hypermethylated in colorectal cancer using bioinformatics analysis." (PMID 28588296, 2017).
glioma (1 paper, 2022). A benign or malignant brain and spinal cord tumor that arises from glial cells (astrocytes, oligodendrocytes, ependymal cells). "Of the 508 patients with glioma, the expression of PCDH18 (p < 0.001), DEPP1 (p < 0.001), VASN (p < 0.001), KCNE4 (p < 0.01), MYBPH (p < 0.001) and MARCH4 (p < 0.01) genes was significantly different between G2 and G3." (PMID 39281062, 2022). "Overexpression of PCDH18, PPL, DEPP1, VASN, KCNE4, MYBPH, and C5AR2 genes or low expression of MARCH4 gene in glioma patients was associated with poor survival." (PMID 39281062, 2022). "Overexpression of PCDH18, PPL, DEPP1, VASN, KCNE4, MYBPH, and C5AR2 in glioma and low expression of MARCH4 were associated with poor survival." (PMID 39281062, 2022). "Through TCGA database, we identified that the eight key genes (PCDH18, PPL, DEPP1, VASN, KCNE4, MYBPH, C5AR2, and MARCH4) were associated with the survival of patients with glioma." (PMID 39281062, 2022).
myocardial infarction (1 paper, 2022). Gross necrosis of the myocardium, as a result of interruption of the blood supply to the area, as in coronary thrombosis. "A Study about myocardial infarction revealed overexpression of CDH2, CDH12, PCDH17, and PCDH18 in myocardial infarction vascular smooth muscle cells compared with controls." (PMID 35480311, 2022).
tumor (9 papers, 2012 to 2025). "Compared with matched non-tumor liver tissues, 3/57 (5.3%) HCCs harbored PCDH18 somatic mutations in the tumor tissues, which was validated by Sanger sequencing." (PMID 29075151, 2017). "The methylation status of PCDH18 was significant higher in CRC tissues than in adjacent non-tumor tissues (median, 15.17% vs. median, 0.4438%)." (PMID 28588296, 2017). "Our results suggested that PCDH18 was a putative tumor suppressor with epigenetic silencing in CRC and a potential biomarker for CRC diagnosis." (PMID 28588296, 2017). "PCDH18 was significantly downregulated in primary tumor tissues with PCDH18 hypermethylation compared to that in adjacent normal tissues." (PMID 28588296, 2017). "Univariate independent prognostic analysis showed that age (p < 0.001), tumor grade (p < 0.001), PCDH18 (p < 0.05), PPL (p < 0.01), DEPP1 (p < 0.01), VASN (p < 0.001), KCNE4 (p < 0.001), MYBPH (p < 0.001), C5AR2 (p < 0.01), and MARCH4 (p < 0.01) gene expression levels were significantly different." (PMID 39281062, 2022). "Conversely, TQ treatment resulted in the downregulation of several genes overexpressed in GBM cells, including potential oncogenes like AEBP1, MIAT, GHR, LMO1, ELF3, and genes involved in tumor proliferation and migration such as EPHA4, COL3A1, PCDH10, ROBO1, ADAMTS5, PCDH18, ST8SIA1." (PMID 39874307, 2025).
cancer (5 papers, 2017 to 2022). A tumor composed of atypical neoplastic, often pleomorphic cells that invade other tissues. "Although we did not detect PCDH18 mutations in the EpCAM-positive HCC cell lines, our data suggest that functional suppression of PCDH18, through somatic mutation or other mechanisms, may underlie the EpCAM-positive HCC cancer phenotype." (PMID 29075151, 2017). "With regard to the underlying mechanism of PCDH18 in cancer pathogenesis, there is still little to no studies focusing on the potential role of PCDH18 in CRC." (PMID 28588296, 2017). "In this study, we found that PCDH18 promoter methylation was a common epigenetic event in CRCs, and that cancer-specific aberration could be frequently found in the circulation." (PMID 28588296, 2017).
PCDH18 also shares sentences with these, for which no sentence is quoted: infection (2 papers); asthma (1); breast carcinoma (1); cutaneous melanoma (1); dental caries (1); endometrial cancer (1); head and neck squamous cell carcinoma (1); hepatocellular carcinoma (1); Hydrocephalus (1); lymphoma (1); pulmonary hypertension (1).